STAT3 (signal transducer and activator of transcription 3)
Diseases named in the same sentence as STAT3 in open-access papers (continued):
Sharing a sentence is not in itself a finding about the gene and the disease.
tumor (continued). "A previous study suggested that STAT1 and STAT3 have opposing roles in the tumor process." (PMID 35719940, 2022). "IL6/JAK/STAT3 signaling and TNFα signaling via NFκB were positively enriched in the active clusters, suggesting that cytokine signaling, likely from the microenvironment, triggers tumor cell awakening." (PMID 36008376, 2022). "IL-6 antibody treatment inhibits in vitro cell proliferation and in vivo tumor growth in both ER+ MCF7 cells and TNBC, MDA-MB-231 cells through a blockade of STAT3 activation and associated downregulation of STAT3 target genes including SOCS3, IL6ST and genes involved in angiogenesis." (PMID 35053592, 2022). "In addition, STAT3 can induce hypoxia-inducible factor-1α (HIF1α), another key regulator of angiogenesis, in the tumor microenvironment." (PMID 36557902, 2022). "STAT3 inhibition in CAFs has also demonstrated an anti-tumor effect on CRC." (PMID 36139552, 2022). "Growing evidence also suggests that STAT3 may be a potential molecular target and biomarker of OSCC, and STAT3 inhibitors have shown efficacy in inhibiting OSCC tumor growth and metastasis." (PMID 36231093, 2022). "For tumor cells, STAT3 decreases the production of immuno-stimulatory cytokines such as interferon-γ (IFN-γ) and tumor necrosis factor-α (TNF-α), along with elevated expression of immuno-exhausting cytokines (IL-6, IL-10, transforming growth factor-β [TGF-β], and VEGF)." (PMID 36080223, 2022). "The PTEN works as a tumor suppressor by controlling the gene expression of STAT3." (PMID 35538578, 2022). "For TAMs, studies have found that elevated ROS in the tumor microenvironment contributes to the differentiation of TAMs into the M2 subtype, while the elimination of ROS can inhibit the polarization of M2 macrophages through the STAT3 signaling pathway." (PMID 36424540, 2022). "STAT1:STAT3 heterodimerization hampers the anti-tumor M1 phenotype." (PMID 35406557, 2022). "When complexes loaded with both DOX and siSTAT3 were exposed to ultrasound, the treatment significantly decreased expression of pro-tumor and pro-mitotic factors STAT3, Cyclin D1, and c-Myc, reduced cell viability, and inhibited tumor growth, indicating efficacy for cancer therapy." (PMID 36365214, 2022). "COX-2 may trigger tumor development, likely inducing the expression of antiapoptotic factor STAT3 and increasing levels of MMPs, as well as promoting the migration of malignant cells." (PMID 36497384, 2022). "As we detected elevated IL-10 levels in primary tumor cells expressing PDGFRβ, we hypothesized that overexpressed PDGFRβ might additionally fuel STAT3 activity in ALCL." (PMID 36045346, 2022). "Studies had demonstrated that pyrimethamine could inhibit oncogenic proteins such as STAT3 and NF-κB and induce apoptosis of tumor cells when synergized with temozolomide." (PMID 36355508, 2022). "IL-6/STAT3 signaling pathway has been shown to regulate TAMs polarization in tumor." (PMID 35193986, 2022). "Therefore, a clearer understanding of the regulatory mechanisms between STAT3 and autophagy will help the R&D of new drugs targeting the STAT3-autophagic pathway and shed new light on tumor prevention and treatment." (PMID 35559037, 2022). "Previous studies have demonstrated that STAT3 has a key role in tumor immune tolerance." (PMID 34976223, 2022). "Moreover, in the tumor microenvironment, the endogenous negative regulators of the STAT3 signaling pathway are downregulated, resulting in enhanced proliferation and malignancy of tumor cells." (PMID 36557902, 2022). "Herein, our in vitro results demonstrated that a low concentration of nintedanib (1 μM) can promote STAT3 phosphorylation and downstream protein expression (PD-L1 and β2M) in different tumor cell lines (A549, MC38 and LLC) and gradually suppress these pathways at high doses (5 μM)." (PMID 34976211, 2022).
tumor (continued). "On the contrary, inhibition of STAT3 can downregulate the expression of programmed cell death 1 ligand 1 (PD-L1) and enhance the infiltration of T cells into tumor tissues, exhibiting synergistic effect in combination with programmed cell death protein 1 (PD-1)/PD-L1 blockade." (PMID 36559280, 2022). "Therefore, STAT3 activation most likely engages the communication between these types in the OSCC microenvironment promoting tumor progression." (PMID 35844493, 2022). "Numerous studies have indicated leptin, IL-6, and TNF-α could enhance the metastatic properties of tumor cells by activating of NF-KB or STAT3 signal pathway." (PMID 36361525, 2022). "Targeting STAT3 is considered a suitable intervention for treatment of tumours." (PMID 35665592, 2022). "In recent years, it has been found that Stat3 is highly activated in various tumor tissues." (PMID 36439090, 2022). "There is also some evidence pointing out that TAMs can mediate resistance of tumor cells to chemotherapy or radiotherapy by activating STAT3 in the tumor cells, which, again, enhances the proliferation and survival of malignant cells even during treatment with various chemotherapeutics." (PMID 35237673, 2022). "This raises the question of whether the STAT3/NRF2 signaling pathway has an antioxidant effect on tumor cells by protecting them from oxidative stress damage and promoting their survival." (PMID 36557902, 2022). "In addition, RT can promote phosphorylation of STAT3, which can contribute to tumor resistance to radiation." (PMID 35954407, 2022). "Furthermore, IHC staining data showed that GK1 tumours in Pdia4–/– mice had a lower protein level of Vegfa, Vegfb, Vegfc and phosphao‐Stat3 than those in WT mice." (PMID 35170261, 2022). "STAT3 and autophagy play important roles in tumor genesis and development." (PMID 36246567, 2022). "The STAT-3 pathway is involved in metastasis of tumor cells and immunosuppression." (PMID 35703345, 2022). "Indeed, aberrantly activated STAT3 signaling is positively correlated with tumor grade and survival rates of patients with GBM." (PMID 35456975, 2022). "Additionally, STAT3 is activated in the majority of human cancers, as well as being involved in inflammation-induced tumor initiation and progression in cancers, such as those of the breast, brain, prostate, ovary, colon, and others." (PMID 35806366, 2022). "Enhanced STAT3 phosphorylation was observed in tumor-exposed SIRP-α knockdown macrophage." (PMID 35585990, 2022). "CXCL8 secreted by primary ESCC cells can inhibit the function of natural killer cells (NK cells) through the STAT3 pathway, leading to tumor immune escape; therefore, immune-boosting therapeutic strategies targeting CXCL8 may benefit ESCC patients." (PMID 36295640, 2022). "In addition, the expression of phspho-STAT3-positive cells was dramatically reduced in the tumor tissue by100 mg/kg radotinib." (PMID 35503759, 2022). "IL-6, another abundant cytokine present both at tissue and systemic levels in PCa patients, limits NK cell anti-tumor activities, via STAT3 activation, by decreasing MICA/B and ULBPs NK cell-activating ligands, resulting in decrease NK cell killing capabilities." (PMID 36338516, 2022). "Additionally, the amount of B cells in tumor tissues was positively correlated with the expression levels of a list of pro-angiogenic molecules that are located at the downstream of STAT3, as well as the extent of tumor angiogenesis." (PMID 36439137, 2022). "Furthermore, lentivirus-mediated overexpression of STAT3 partially reversed the anti-tumor effect of Stattic." (PMID 35288541, 2022). "Tumor conditioned medium could upregulate CXCL12 expression that facilitated the migration of human BM-MSCs to tumor sites by activating JAK2/STAT3 and MEK/ERK1/2 pathways." (PMID 36324128, 2022).
tumor (continued). "At postnatal day 7, prior to tumor formation by histological examination, pups were randomly assigned to receive the STAT3 inhibitor NSC74859 (50 mg·kg−1) or vehicle control by I.P., every other day for 2 weeks, with 20 mice examined for each group (NSC74859‐treated or control treated)." (PMID 34482626, 2022). "Activation of the Janus kinase-signal transducer and activator of transcription 3 (STAT3) have been demonstrated to play a critical role in tumor development by regulating signaling pathways involved in cell proliferation, survival, metastasis, and angiogenesis in human medicine." (PMID 35836213, 2022). "The granulocyte macrophage-colony stimulating factor (GM-CSF) derived from tumor cells can activate STAT3 signaling pathway to induce the expression of fatty acid transport protein 2 (FATP2), which promotes lipids accumulation and enhances the immunosuppressive function in MDSCs." (PMID 35062950, 2022). "mTOR-mediated regulation of STAT3 and NF-κB activity promoted an immunosuppressive microglial phenotype, which hindered effector T-cell infiltration, proliferation, and immune reactivity, thereby contributing to tumor immune evasion and tumor aggression." (PMID 35600367, 2022). "In gliomas, STAT3 is a critical determinant of tumour associated immunosuppression and shows a negative correlation with miR‐124." (PMID 34618359, 2022). "In addition, an increase in STAT3 activation upregulates carcinoembryonic antigen-related cell adhesion molecule 5, which plays a pivotal role in cell adhesion, migration, tumor invasion and metastasis in CRC." (PMID 35954156, 2022). "Under hypoxic conditions, the expression of CAIX (carbonic anhydrase IX) regulated through EGFR/STAT3/HIF-1α axis significantly increased in GBM, contributing to the polarization of tumor-associated monocytes/macrophages (TAM) toward a more tumor-supportive phenotype." (PMID 35600367, 2022). "These are critical questions regarding Cad11/Stat3 in Src Biology and neoplasia." (PMID 35411090, 2022). "Several studies have demonstrated that CXCR7 may be involved in tumor-associated signaling pathways, including PLC/MAPK, ERK1/2, STAT3 and AKT pathways, which have been revealed to play a prominent role in tumor cell adhesion, invasion and metastasis." (PMID 35768814, 2022). "Moreover, pharmacological inhibition or genetic inactivation of the IL-6/STAT3 pathway inhibits the invasive capacity of tumor cells, and hence, prevents metastatic colonization in PDAC." (PMID 35993361, 2022). "The curcumin–EGCG combination inhibited angiogenesis in CM-induced tumor cells through suppression of the JAK/STAT3 pathway, and the inhibitory effects on tumor growth and angiogenesis were evidently greater in a xenograft mouse model than those observed after EGCG or curcumin monotreatment." (PMID 36557939, 2022). "Similar to tumor cells, STAT3 is required for invasive properties in trophoblasts." (PMID 35215985, 2022). "Additionally, CAFs can release TGF-β leading to activation of STAT3 signaling pathway in tumor cells." (PMID 35650297, 2022). "Previous studies have focused on STAT-3, IL-6R and IL-6 pathways as enhancers of tumor progression." (PMID 35703345, 2022). "In pancreatic ductal adenocarcinoma, researchers have found that the extracellular release of KRASG12D during autophagy-dependent ferroptosis can drive macrophages to switch to an M2-like pro-tumor phenotype via STAT3-dependent fatty acid oxidation, finally promoting tumor growth." (PMID 36568375, 2022). "AQP3/STAT3/CD133 signaling plays a major role during tumor progression in HCC." (PMID 35820920, 2022).
tumor (continued). "Importantly, HCC cells with elevated TLR4 expression are sensitive to TLR4-mediated tumor promotion through the activation of Akt, NF-κB and STAT3 signaling and the downregulation of let-7 miRNA." (PMID 35955552, 2022). "Crucial transcription factors like STAT3 and NF-κB in precancerous cells are activated by pro-inflammatory cytokines which can lead to genetic modifications, thereby promoting tumor survival." (PMID 35990411, 2022). "Furthermore, in this study, we aimed at dissecting the activation of STAT1 and STAT3 in tumor cells and the immune cell infiltrate in human HCC tissue samples." (PMID 35267462, 2022). "Notably, our data demonstrated that RT provided protection against the activation of STAT3, overabundance of IL-6, and oxidative stress-mediated muscle atrophy in tumor-bearing mice." (PMID 35847939, 2022). "Silencing of STAT3 partially prevented TRIM47–induced tumor cell proliferation and invasion." (PMID 36288633, 2022). "However, one emerging target is IL-6, which activates signal transducer and activator of transcription 3 (STAT3) signalling within tumour cells." (PMID 35020853, 2022). "However, at least one study reports that macrophage and myeloid STAT3 hyperactivation offers anti-tumor benefits." (PMID 35406557, 2022). "Overexpression of STAT3 can be detected in a variety of tumor tissues and cells." (PMID 36246567, 2022). "Furthermore, ER-stressed HCC cells can promote cytokine expression through exosome-mediated activation of the JAK2/STAT3 pathway in macrophages, which leads to macrophage immunosuppression and tumor progression." (PMID 36531059, 2022). "Further, we found that the expression of BCL-2 downstream of JAK2/STAT3 was also reduced, and BCL-2 was associated not only with apoptosis but also with the infiltration of immune cells in the immune microenvironment of the tumor." (PMID 36582521, 2022). "Stat3 is involved in many cellular processes, including oncogenesis, tumor growth, and diffusion." (PMID 36291778, 2022). "Mir-29 is down-regulated in tumor cells, with many ectopic productions of mir-29, which reduces the expression of stem cell-related transcription factors and their capacity to form pellets, activates the STAT3 signaling pathway, raises STAT3 expression, and promotes tumor pathogenesis." (PMID 35113040, 2022). "Interestingly, contrary to its accepted tumor-promoting role, a fraction of research has shown an opposite role of STAT3 in cancer cells." (PMID 36231093, 2022). "STAT3 acts mainly to promote tumor growth and immunosuppression." (PMID 36291659, 2022). "In this context, our data support the growing body of evidence that STAT3 may represent a potential therapeutic target to overcome CRT resistance in various tumor entities." (PMID 35267609, 2022). "Dysregulation of STAT3 and enhanced expression of the active phospho-form not only within the tumor cells themselves but also within the TILs, including fibroblasts constituting the tumor microenvironment can support solid tumor growth." (PMID 35844493, 2022). "Notably, the results of the possible tumor-suppressive roles of STAT3 in a CRC mouse model require further investigation regarding the underlying molecular mechanisms and consistency with clinical observations." (PMID 36010693, 2022). "The joint activation of these G protein-coupled receptors induces the activation of the tyrosine-kinase effector GSK3 to induce cell proliferation, cell migration, and colony formation possibly via alteration of MUC1, NOTCH, and STAT3 expression resulting in a more aggressive tumor profile." (PMID 35568869, 2022). "Except immunomodulation, the mechanism of tumor growth inhibition may be related to the regulation of apoptosis related proteins and IL-6/STAT3 pathway." (PMID 35577774, 2022).
tumor (continued). "Moreover, suppression of PELP1 reduced tumor growth and angiogenesis in vivo accompanied by inactivation of STAT3/VEGFA pathway." (PMID 35053547, 2022). "Moreover, western blotting assessments of FGFR4 and p‐STAT3 in xenograft tumour lysates revealed that, consistent with the in vitro results, DCZ0415 inhibited the expression of these proteins." (PMID 35194944, 2022). "We also provide evidence that the RV-promoted switch toward quiescence was sustained by negative feedback on the IL-6R/STAT3 pathway, which has been associated with tumor growth, angiogenesis, chemoresistance, and immune suppression." (PMID 35565270, 2022). "To explore a mechanistic link between tumor-infiltrating neutrophils and iCAF-mediated IL-6/STAT-3 signaling in the PDAC TME, we characterized the secretome of tumor-infiltrating Ly6G+F4/80- neutrophils isolated from orthotopic KPC tumors, revealing IL-1β as the most robustly secreted cytokine." (PMID 36107485, 2022). "Moreover, STAT3 is an indispensable key molecule in the process of chronic inflammation promoting tumorigenesis and tumor-related inflammation." (PMID 36188592, 2022). "The high expression of STAT3 thus enhances immune escape ability or establishes immune tolerance through a variety of mechanisms, and the inflammatory microenvironment further promotes tumor angiogenesis and the growth, invasion and metastasis of tumor cells." (PMID 36591515, 2022). "STOML2 promotes tumor progression by upregulating IL-6 to promote STAT3 pathway." (PMID 35851063, 2022). "Recently, it has been demonstrated that inhibition of STAT3 leads to a reduction in PD-L1 protein expression, which may constrain tumoral inflammation and improve immune response against tumor cells." (PMID 35267462, 2022). "However, several studies have shown that PD-L1 expression can be upregulated on various types of tumor cells by the activation of the STAT3 and PI3K-Akt pathways when CXCL9 is stimulated by IFN-gamma signaling." (PMID 36362062, 2022). "The tumor suppressive role of SHP-1, encoded by PTPN6 gene, has been made clear by reports of its negative regulation of several key oncogenic tyrosine kinases such as the JAK kinases and STAT3." (PMID 35941532, 2022). "To investigate whether the forced overexpression of STAT3 promotes tumor growth in vivo, we implanted STAT3-overexpressing and control H146 cells in the flanks of nude mice." (PMID 35885009, 2022). "In summary, targeting STAT3 might be an attractive approach in restoring NK-cell anti-tumor immunity but needs to be carefully evaluated in different tumor types and biological contexts." (PMID 35865518, 2022). "It suggests that tumor inhibition of SHF probably underlies the regulation of STAT1 independent of STAT3, a question worthy of further exploration." (PMID 35843865, 2022). "Moreover, Stat3 that induces tumor progression via supporting tumor survival, angiogenesis, and suppressing antitumor immunity is activated by IL-17." (PMID 36078902, 2022). "The STAT3 pathway is often constitutively active in HGGs, and STAT3 activation induces the secretion of immunosuppressive cytokines, suppressing T cell expansion and promoting Tregs recruitment, and promotes tumor angiogenesis." (PMID 36186781, 2022). "Similarly, deletion of lung epithelial STAT3 in a urethane-induced LUAD model improved NK cell tumor killing function." (PMID 35406557, 2022). "Similarly, IL-6 produced by CAFs was evidenced to endow tumor-initiating characteristics to HCC cells by the enrichment of STAT3/Notch signaling." (PMID 36293184, 2022). "In subcutaneous and orthotopic transplantation mouse tumour models, the STAT3 inhibitor napabucasin prevented tumour growth and induced the expression of calreticulin and the protein disulfide isomerase family A member 3 (PDIA3; also known as ERp57) but suppressed that of CD47 and GLUT1." (PMID 35665592, 2022).